RPS14 (ribosomal protein S14)
Description:
Component of the small ribosomal subunit. The ribosome is a large ribonucleoprotein complex responsible for the synthesis of proteins in the cell. Part of the small subunit (SSU) processome, first precursor of the small eukaryotic ribosomal subunit. During the assembly of the SSU processome in the nucleolus, many ribosome biogenesis factors, an RNA chaperone and ribosomal proteins associate with the nascent pre-rRNA and work in concert to generate RNA folding, modifications, rearrangements and cleavage as well as targeted degradation of pre-ribosomal RNA by the RNA exosome.
Synonyms: EMTB; S14; uS11
Tractability: Small molecule: an approved drug acts on it; a structure with a bound ligand is known; a high-quality ligand is known. PROTAC: UniProt records ubiquitination sites on it; ubiquitination databases record sites on it; its protein half-life has been measured; a small molecule that binds it is known. Other modalities: a drug acting on it is in phase 2 or 3 trials.
Target class: Other cytosolic protein
Gene: Protein-coding gene on chromosome 5 (150,442,635 to 150,449,952, reverse strand). Ensembl gene ENSG00000164587.
Subcellular location: Cytoplasm; Nucleus, nucleolus
Subcellular location (Human Protein Atlas): Cytosol; Endoplasmic reticulum
Pathways (Reactome):
Metabolism of proteins: Eukaryotic Translation Termination; Formation of a pool of free 40S subunits; Formation of the ternary complex, and subsequently, the 43S complex; GTP hydrolysis and joining of the 60S ribosomal subunit; L13a-mediated translational silencing of Ceruloplasmin expression; PELO:HBS1L and ABCE1 dissociate a ribosome on a non-stop mRNA; Peptide chain elongation; Ribosomal scanning and start codon recognition; SRP-dependent cotranslational protein targeting to membrane; Translation initiation complex formation; ZNF598 and the Ribosome-associated Quality Trigger (RQT) complex dissociate a ribosome stalled on a no-go mRNA
Metabolism of RNA: Major pathway of rRNA processing in the nucleolus and cytosol; Nonsense Mediated Decay (NMD) enhanced by the Exon Junction Complex (EJC); Nonsense Mediated Decay (NMD) independent of the Exon Junction Complex (EJC); rRNA modification in the nucleus and cytosol
Disease: SARS-CoV-1 modulates host translation machinery; SARS-CoV-2 modulates host translation machinery; Viral mRNA Translation
Cellular responses to stimuli: Response of EIF2AK4 (GCN2) to amino acid deficiency
Developmental Biology: Regulation of expression of SLITs and ROBOs
Metabolism: Selenocysteine synthesis
Gene Ontology:
Molecular function: mRNA 5'-UTR binding; protein binding; RNA binding; structural constituent of ribosome
Biological process: cytoplasmic translation; erythrocyte differentiation; negative regulation of transcription by RNA polymerase II; ribosomal small subunit biogenesis; maturation of SSU-rRNA; ribosomal small subunit assembly; translation
Cellular component: cytoplasm; cytosol; cytosolic ribosome; cytosolic small ribosomal subunit; endoplasmic reticulum; extracellular exosome; focal adhesion; membrane; nucleolus; postsynaptic density; small-subunit processome; nucleoplasm; ribosome; synapse
Genetic constraint (gnomAD): Loss-of-function variants: 1 observed, 15.59 expected, observed/expected ratio (o/e) 0.0641, 90% interval 0.022 to 0.3. The upper end of that interval is the gene's LOEUF score, 0.3, which puts it in group 1 of 6, group 1 being the genes least tolerant of losing a copy. Missense variants: 69 observed, 208.78 expected, observed/expected ratio (o/e) 0.33, 90% interval 0.27 to 0.4. Synonymous variants: 67 observed, 74.97 expected, observed/expected ratio (o/e) 0.89, 90% interval 0.73 to 1.1.
Homologues: Orthologues: chimpanzee RPS14 (100% identical), dog RPS14 (100% identical), guinea pig RPS14 (100% identical), mouse Rps14 (100% identical), pig RPS14 (100% identical), rabbit RPS14 (100% identical), rat Rps14 (100% identical), tropical clawed frog rps14 (100% identical), zebrafish rps14 (99% identical), macaque RPS14 (91% identical), rat LOC120101650 (89% identical), Caenorhabditis elegans rps-14 (87% identical), and 2 more. Paralogues in human: MRPS11 (29% identical).
Diseases named in the same sentence as RPS14 in open-access papers:
RPS14 is named in the same sentence as 56 diseases in open-access papers, as found by Europe PMC text mining. Sharing a sentence is not in itself a finding about the gene and the disease. The quoted sentences say what the papers report.
anemia (16 papers, 2014 to 2025). A reduction in the number of red blood cells, the amount of hemoglobin, and/or the volume of packed red blood cells. "Ebert and colleagues showed through RNA interference experiments that deficient expression of RPS14 in MDS-del(5q) was responsible for the development of anemia; enforced expression of RPS14 rescues the disease phenotype in patient-derived bone marrow cells." (PMID 41440765, 2025). "RPS14 deficiency leads to anemia, while overexpression rescued erythropoiesis, and this was linked to TGF-β-mediated MMP-9 expression." (PMID 38732249, 2024). "5q-syndrome is a type of anemia that is caused by the haplo-insufficiency of RPS14, a critical component for 40S assembly, and depletion of RPS14 in human CD34+ cells is sufficient to recapitulate the 5q-defect of erythropoiesis with sparing of megakaryocytes." (PMID 33435549, 2021). "A zebrafish homozygous rps14 loss-of-function mutant also develops anemia with a terminal erythroid maturation defect equivalent to that observed in 5q− syndrome." (PMID 29255698, 2017). "Notably, only one deficient ribosomal protein, RPS14, is identified in 5q- syndrome, which is another type of anemia diagnosed with macrocytic anemia and micromegakaryocytes accompanied with a low risk of developing into acute myeloid leukemia." (PMID 31619461, 2019). "The development of anemia in these patients seems to be related to haploinsufficiency and consequent reduced expression of RPS14." (PMID 41440765, 2025). "Defects in several ribosomal proteins including RPS19, RPL11 and RPS14 have been observed in two types of anemia: Diamond Blackfan Anemia and 5q- syndrome." (PMID 31619461, 2019). "Treatment of embryos with amino acid L-Leucine, a potent activator of the mTOR pathway and mRNA translation, has been shown to alleviate anemia in rps14 and rps19 morpholino knock-down zebrafish embryos." (PMID 26624285, 2015). "It has been shown that the 35 A > G mutation in the gene for ribosomal protein S14 (rps14), a candidate gene for 5q-syndrome, a distinct form of mylodysplastic syndrome (MDS), causes erythroid failure and anemia in zebrafish, similar to what is observed in human patients." (PMID 36869044, 2023). "Indeed, l-leucine, a drug in testing for DBA, has already proven effective in treatment of both mutant Rps14- and Rps19-driven anemia in zebrafish." (PMID 29255698, 2017). "In 2008, Ebert and colleagues identified RPS14 as a major driver of 5q− anemia." (PMID 29255698, 2017). "It has been demonstrated that haploinsufficiency of ribosomal proteins Rps14 and Rps19 causes symptoms resembling DBA in zebrafish such as anemia and craniofacial dysplasia, and also that treatment with L-Leucine reduces the severity of both anemia and developmental deficits." (PMID 24550838, 2014). "Based on this, some conditional Rps14 knockout MDS models have been generated, that have developed a progressive anemia." (PMID 34179724, 2021).
myelodysplastic syndrome (16 papers, 2015 to 2025). A clonal hematopoietic disorder characterized by dysplasia and ineffective hematopoiesis in one or more of the hematopoietic cell lines. "RPS14, a component of the 40S ribosomal subunit, is involved in erythroid differentiation and has been implicated in hematological disorders such as myelodysplastic syndrome and 5q syndrome." (PMID 40978038, 2025). "RPS14 haploinsufficiency is associated with myelodysplastic syndrome with chromosome 5q deletion." (PMID 36518216, 2022). "The acquired haploinsufficiency of RPS14 has been shown to underlie the erythroid defect in 5q-myelodysplastic syndrome (MDS)." (PMID 26398160, 2015). "S100A9 was also shown to suppress erythroid differentiation in both experimentally induced deletion 5q subtype of myelodysplastic syndrome through inactivation of Rps14 and wild-type mouse model, specifically the hematopoietic stem cells and progenitor cells." (PMID 37146011, 2023). "In the 5q syndrome, a subtype of adult myelodysplastic syndrome, the long harm of chromosome 5 is deleted, resulting in uS11/RPS14 haploinsufficiency and subsequent severe refractory anemia." (PMID 29674660, 2018). "Ribosomes have been presented to be related to cell proliferation, growth and apoptosis, and low expression of RPS14 had been found in myelodysplastic syndrome patients." (PMID 27791988, 2017). "The deletion of RPS14 is closely related to del(5q) myelodysplastic syndrome (MDS)." (PMID 35841000, 2022). "Prominent examples are RPS14/uS11, RPSA/uS2 and RPL38/eL38 genes with mutations associated with 5q- myelodysplastic syndrome, isolated congenital asplenia and skeletal defects during embryogenesis, including perturbations in the formation of the axial skeleton." (PMID 33575632, 2020). "The acquired myelodysplastic syndrome 5q‐, characterized by a deletion of a region of chromosome 5q, is also considered a ribosomopathy due to the presence of the RPS14 gene in the deleted region and the phenotypic recapitulation of much of the disease phenotype upon deletion of RPS14 alone." (PMID 31148378, 2019). "Similarly, RPS14 (uS11) haploinsufficiency has been reported in the 5q- myelodysplastic syndrome (MDS)." (PMID 28147343, 2017).
breast carcinoma (6 papers, 2021 to 2025). "The oncogenic role of RPS14 was further determined regarding the proliferation and metastasis of estrogen receptor-positive breast cancer cells." (PMID 36059657, 2022). "From the results, we found that mRNA expressions of SLC19A1, CYC1, RRM2B, and OCRL were clearly elevated in breast cancer, while RPS14 expression was considerably decreased." (PMID 35574387, 2022). "And for the survival analyses of OS, high expressions of SLC19A1, CYC1, RRM2B, and OCRL and downregulation of RPS14 were significantly related to more unfavorable OS in breast cancer, which further confirmed the validity of selected genes." (PMID 35574387, 2022). "The ribosomal protein S14 (RPS14), which was identified to be associated with the cancer-prone 5q-syndrome, was also found to negate c-Myc functions and promotes the proliferation and metastasis of estrogen receptor-positive breast cancer cells." (PMID 35574387, 2022). "Contradicting our results, previous studies have shown that low expression levels of ribosomal proteins RPS9, RPS14, RPS27, RPL11 and RPL14 are related to a poor overall survival in breast cancer patients, especially in TNBC." (PMID 37888706, 2023). "In a previous report, Fang and Zhang used integrated bioinformatics analyses and identified that low mRNA expression of RPL11, RPS14, RPS9, and RPL10A were related to a worse overall survival of breast cancer patients." (PMID 33718123, 2021). "Furthermore, studies have shown that in oestrogen receptor (ER)‐positive breast cancer tissues, RPS14 is highly expressed compared with ER‐negative breast cancer and that reducing the expression of Rps14 inhibits cell proliferation and metastasis." (PMID 36977657, 2023). "By performing the LASSO Cox regression analysis with 9 candidate genes in breast cancer patients of TCGA-BRCA training dataset, 5 pivotal genes were unearthed to establish the prognostic signature, Lactate Metabolism Index, namely LMI, including RPS14, SLC19A1, CYC1, RRM2B, OCRL." (PMID 35574387, 2022).
macrocytic anemia (6 papers, 2012 to 2024). Anemia that is characterized by increased red blood cell volume. "RPS14 mutations underlie 5q- syndrome, an acquired ribosomopathy that is characterized by macrocytic anemia and cancer predisposition." (PMID 27784267, 2016). "Typically, ribosomal protein S14 (RPS14) and casein kinase 1 alpha 1 (CSNK1A1) are associated with the dysplasia of erythrocytes, and RPS14 haploinsufficiency contributes to macrocytic anemia in mutant erythroblasts." (PMID 38616283, 2024). "For instance, RPS14 has been implicated in the pathogenic mechanisms of cytopenias, including MDS with 5q deletion and congenital macrocytic anemias." (PMID 37958462, 2023). "Acquired uniallelic deletion of RPS14 gene has also been shown to lead to the 5q syndrome, a distinct subset of MDS associated with macrocytic anemia." (PMID 22709827, 2012).
colon cancer (5 papers, 2022 to 2025). "Among the ribosomal proteins that we observed to be associated with our EC samples, RPS18 and RPL18A have been previously reported in association with colon cancer and RPS14 and RPS18 in prostate cancer." (PMID 37760635, 2023). "In colon cancer, overexpression of RPS14 has been reported to activate the PI3K/Akt signaling pathway, enhancing tumor cell survival." (PMID 40978038, 2025). "We also confirmed through experiments that two C-to-U RESs in CSNK2B or RPS14 had different effects on colon cancer cells." (PMID 36969056, 2023). "The correlation between CD4+ T cells and RPS14 (correlation = −0.5) was the highest in colon cancer while CD8+ T and RPS2 (correlation = −0.53) was the highest in rectal cancer." (PMID 35127345, 2022). "Importantly, we experimentally validated two C-to-U RESs, in CSNK2B (casein kinase II beta subunit) and RPS14 (ribosomal protein S14), respectively, with different impacts on cell proliferation in colon cancer." (PMID 36969056, 2023). "In colon cancer, the highest correlation was found between CD4+ T cells and RPS14 (correlation = −0.5) and CD4+ T and RPS15A (correlation = −0.49), as well as dendritic cells and RPS3 (correlation = −0.49)." (PMID 35127345, 2022).
Diamond-Blackfan anemia (5 papers, 2008 to 2025). A congenital aregenerative and often macrocytic anemia with erythroblastopenia. "Somatic heterozygous loss of RPS14 (uS11) has been implicated in disorders such as 5q syndrome and Diamond-Blackfan anemia (DBA), both of which present with a tumor-prone phenotype." (PMID 39656543, 2025). "For example, the Diamond-Blackfan Anemia (DBA) is caused by heterozygous loss-of-function mutations in genes encoding RPs, such as RPS19, RPL5, and RPL11, while the 5q-syndrome is caused by a somatically acquired deletion of chromosome 5q, which leads to haploinsufficiency of RPS14." (PMID 30862090, 2019). "We have recently demonstrated haploinsufficiency of the ribosomal gene RPS14 in the haematopoietic stem cells (HSC) in patients with the 5q− syndrome and have suggested that it represents a good candidate gene based on analogy with Diamond-Blackfan anaemia (DBA)." (PMID 18477045, 2008).
HCMV infection (5 papers, 2016 to 2024). "Since RPS14 was reported to interact with MDM2 during ribosomal stress, the outcome of the MDM2-RPS14 interaction during HCMV infection and emetine treatment was investigated." (PMID 27336364, 2016).
viral infection (5 papers, 2009 to 2025). "There were, however, differences between the two cell types tested; for example, RPS14 knockdown strongly inhibited viral infection in NHBE but not A549 cells, and knockdown of NUP98 was inefficient in NHBE cells despite inhibiting virus in A549 cells." (PMID 29775471, 2018).
colorectal cancer (3 papers, 2022 to 2024). A primary or metastatic malignant neoplasm that affects the colon or rectum. "RPS14 overexpression promoted the development of colorectal carcinoma, and RPS14, a downstream target of zinc finger protein 280 A (ZNF280A), was upregulated in melanoma cells and has a co-binding site for YAP and β-catenin via LEF1/TEAD." (PMID 38388496, 2024). "Because FIRΔexon2 is detected in colorectal cancer tissues, the expressions of RPL30, RPL37A, RPL38, RPS14, and RPS29 mRNAs by the effect of FIRΔexon2 were examined in HCT116 cells." (PMID 38139171, 2023).
bladder cancer (2 papers, 2021 to 2022). "In solid tumors, some bioinformatics analyses found the association between RPS14 and triple-negative breast cancer, as well as bladder cancer." (PMID 36059657, 2022). "Based on bioinformatics analysis, RPS14 was identified as hub gene of bladder carcinoma." (PMID 33305312, 2021).
glioblastoma (2 papers, 2020 to 2022). The most malignant astrocytic tumor (WHO grade IV). "Finally, the present study allowed us to identify prognostic proteins for glioblastoma: PPP1R12A and RPS14 are favorable prognostic markers while ALCAM, ANXA11, and AltProt IP_652563 are unfavorable prognostic markers." (PMID 36333286, 2022).
glioma (2 papers, 2019 to 2025). A benign or malignant brain and spinal cord tumor that arises from glial cells (astrocytes, oligodendrocytes, ependymal cells).
Alzheimer disease (1 paper, 2024). A progressive, neurodegenerative disease characterized by loss of function and death of nerve cells in several areas of the brain leading to loss of cognitive function such as memory and language. "Notably, six of these proteins (RPS3A, RPS4X, RPS8, RPS14, RPS20 and RPL31) were upregulated in brain capillaries of Alzheimer’s disease patients." (PMID 38732249, 2024).
aplastic anemia (1 paper, 2014). Anemia resulting from bone marrow failure (aplastic or hypoplastic bone marrow). "Interestingly, one of these aplastic anemia patients has slightly higher eADA activity and a copy number neutral 5q loss of heterozygosity in the region of the RPS14 gene, raising the possibility of a functional connection between RP haploinsufficiency and dysferlin accumulation in RBCs." (PMID 24454878, 2014).
blood disease (1 paper, 2023). A disease that occurs in the blood. "RPS14 has been reported to promote malignant tumour metastasis and is associated with blood diseases." (PMID 36604982, 2023).
cervical intraepithelial neoplasia (1 paper, 2025). "This study evaluated the diagnostic value of ALK, RPS14 genes, and key components of the PI3K/Akt/NF - κ B pathway for high-grade cervical intraepithelial neoplasia (HSIL) through ROC curve analysis." (PMID 40978038, 2025).
COVID-19 (1 paper, 2021). A disease caused by infection with severe acute respiratory syndrome coronavirus 2. "NKTR and its PPI partners transcription initiation factor TFIID subunit 1 (TAF1), 40S ribosomal protein S14 (RPS14), and arrestin beta 2 (ARRB2) are differentially expressed in the PBMCs of COVID-19 patients." (PMID 34108016, 2021).
depression (1 paper, 2024). "In particular, ribosomal protein S19, ribosomal protein S12, ribosomal protein S14, vimentin, and ubiquitin-like modifier activating enzyme 1 mediated the therapeutic effects of EXD on depression and hippocampal damage." (PMID 38915473, 2024).
diabetes (1 paper, 2022).